SPARC (secreted protein acidic and cysteine rich)
Diseases named in the same sentence as SPARC in open-access papers (continued):
Sharing a sentence is not in itself a finding about the gene and the disease.
Obesity (continued). "Therefore, elevated levels of SPARC to counteract the obesity state and its complications may no longer be needed." (PMID 37436597, 2023). "Indeed, HFD-induced obesity is enhanced in the absence of SPARC." (PMID 35208200, 2022). "After reducing the influence of obesity by BMI matching and/or statistical adjustments for BMI in interpretation of our data and study of expression in human islets expressions rather than adipocytes, we found a significant reduction of SPARC expression in islets from subjects with diabetes." (PMID 23840838, 2013). "Whilst obesity related adipose tissue fibrosis may well attribute to insulin resistance as also shown by increased levels of ECM components such as collagen VIalpha3, the multifunctional protein SPARC appears to influence more than one pathway of glucose and insulin metabolism." (PMID 23840838, 2013).
lung carcinoma (41 papers, 2008 to 2025). "The SPARC gene codifies a matricellular protein that is implicated in the regulation of tissue remodeling, cell proliferation and migration in lung cancer, chronic airway disease, and pulmonary fibrosis." (PMID 40970095, 2025). "On the other hand, SPARC downregulation in malignant gliomas inhibits cancer cell migration and invasiveness and in lung cancer SPARC has been associated with increased growth and metastatic potential." (PMID 35917053, 2022). "On the other hand, high expression of SPARC in the stroma is associated with poor overall survival in lung cancer patients." (PMID 30227835, 2018). "It is paradoxical that lung cancer stroma cells expressing SPARC are associated with poor prognoses and lung cancer-expressing SPARC is associated with good prognoses." (PMID 28969021, 2017). "In lung cancer patients, high SPARC expression in lung stroma cells is associated with poor prognosis." (PMID 28969021, 2017). "Interestingly, SPARC overexpression by tumor-associated fibroblasts in pancreatic and lung cancer is also a marker of bad prognosis despite the fact that the malignant cells themselves are SPARC-negative due to promoter hypermethylation." (PMID 19337591, 2009). "Given the known epidemiologic link between IPF and lung cancer, and shared pathogenic features such as senescence, chronic injury, and aberrant epigenetic reprogramming, it is plausible that SPARC silencing may participate in a common disease axis." (PMID 40970095, 2025). "In contrast, in lung cancer cells where SPARC protein expression is low, HDAC10 depletion had minimal effect on colony or spheroid growth." (PMID 38650694, 2024). "The bioinformatics-based association analysis identified candidate exosomal proteins associated with lung cancer, including SPP1, CD44, ALB, SPARC, CAT, GAPDH, and CADM1." (PMID 39766023, 2024). "The top candidate exosomal proteins associated with lung cancer, based on the number of publications supporting the association, included SPP1, CD44, ALB, SPARC, CAT, GAPDH, and CADM1." (PMID 39766023, 2024). "SPARC has the advantage of promoting, invading, and migrating lung cancer cells, making it a novel therapeutic target." (PMID 37577749, 2023). "Network pharmacology and experimental studies have continuously confirmed the strong presence of SPARC in lung cancer." (PMID 37577749, 2023). "SPARC expression was upregulated in lung cancer cells via promoter demethylation and is correlative with a decreased DNA methyltransferase (DNMT) activity." (PMID 37577749, 2023). "SPARC is a biologically relevant mechanism that is upregulated in the development of lung cancer as a specific site that regulates collagen binding." (PMID 37577749, 2023). "SPARC is also highly expressed in fibroblasts (LFC: 2.76), which has been associated with bone-related breast and lung cancer invasion and metastasis." (PMID 37479733, 2023). "The positive representation rate of SPARC in stages I and II lung cancer was significantly lower than that in stages III and IV lung cancer." (PMID 37577749, 2023). "There is controversy in the literature on the role of SPARC in cancer, but, specifically for lung cancer, it has been shown to be a poor prognostic indicator as it promotes tumor metastasis." (PMID 35804837, 2022). "The levels of COL10A1 and SPARC were significantly higher in lung cancer patients compared to healthy controls." (PMID 33066583, 2020). "We demonstrated here that aberrant methylation of SPARC promoter region should be considered a frequent event in lung cancer cell lines from different histologies and NSCLC patients." (PMID 32580473, 2020). "Anyhow, the data concerning the epigenetic mechanism of SPARC deregulation and its prognostic value in lung cancer are still incomplete." (PMID 32580473, 2020).
lung carcinoma (continued). "Strikingly, three early EMT hallmark genes GALNT6, SPARC and HES7 show the similar stage-specific expression pattern in LUAD TCGA samples, which can be further studied for diagnosis of early stages of lung cancer and for developing anticancer drugs." (PMID 31296175, 2019). "As already assessed SPARC was significantly strongly elevated in lung cancer patients compared to healthy controls (p < 0.001) and remained significant across gender subgroups (p < 0.001)." (PMID 30227835, 2018). "a ROC curve of SPARC evaluating the capability of SPARC levels to discriminate between lung cancer patients and controls, with AUC and its bootstrap 95% CI." (PMID 30227835, 2018). "Although SPARC has recently emerged as a prognostic biomarker in different tumors, its role in lung cancer remains controversial." (PMID 30227835, 2018). "Soluble factors related to proficient tumor-stroma cross-talk are detectable in plasma of primary lung cancer patients and may represent a valuable complementary diagnostic tool to discriminate lung cancer patients from healthy heavy-smokers individuals as shown for the SPARC protein." (PMID 30227835, 2018). "The effect of SPARC was examined in tumor-bearing C57BL/6 mice which were intravenously injected with the murine lung cancer cells LLC1." (PMID 28969021, 2017). "Overexpression of KLF4 inhibits invasiveness of lung cancer cells (A549 and H322) by suppressing SPARC expression." (PMID 28969021, 2017). "SPARC promotes growth and inhibits the apoptosis of lung cancer cells." (PMID 37577749, 2023). "Plasma of lung cancer patients contains overexpressed SPARC." (PMID 37577749, 2023). "Other important glycoproteins present in lung cancer are the SPARC and WNTs." (PMID 36452484, 2022). "At present, the data concerning methylation as possible epigenetic mechanisms of SPARC deregulation in lung cancer are incomplete and correlation analysis with disease clinical course in a specific subset of patients or specific therapeutic strategies is lacking." (PMID 32580473, 2020). "In tumorigenesis, SPARC presents a downregulated pattern in specific tumor cell types (e.g., epithelial) and an upregulated pattern in adjacent stromal cells, as described in ovarian, pancreatic and lung cancers." (PMID 33383671, 2020). "Andriani and colleagues reported that plasma samples from patients with lung cancer had significantly higher levels of collagen 10a1 and the collagen-binding matricellular protein SPARC compared with healthy controls who were matched for clinical parameters, such as sex, age, and smoking status." (PMID 30678058, 2019). "SPARC protein levels in plasma were high in all stages of the disease indicating that this could also serve as marker of early lung cancer." (PMID 30227835, 2018). "Moreover, it has been reported that overexpression of Snail leads to upregulation of secreted proteins, acidic and rich in cysteine (SPARC) in models of premalignancy and established disease, as well as in lung carcinoma tissues in situ." (PMID 29499705, 2018). "Therefore, in both univariable and multivariable analyses, SPARC levels resulted higher in the presence of lung cancer." (PMID 30227835, 2018). "However, the role of SPARC in lung cancer is paradoxical and details of the regulatory mechanism are not well-known." (PMID 28969021, 2017). "This evidence might imply that stroma cell-secreted SPARC plays a different role from SPARC in lung cancer." (PMID 28969021, 2017). "Lung cancer growth may be inhibited by the elevated level of SPARC mRNA in lung cancer tissues." (PMID 37577749, 2023). "The aim of the present study was to measure the levels of three circulating ECM related proteins (COL11A1, COL10A1 and SPARC) in plasma samples of lung cancer patients and in healthy heavy-smokers controls and test whether such measurements have diagnostic or prognostic value." (PMID 30227835, 2018).
lung carcinoma (continued). "Cleavage of SPARC extracellular Ca2+ binding domain by MMP‐8 and MMP‐13 has been detected in the serum of patients with lung cancer, suggesting their presence also in vivo." (PMID 36346290, 2023). "The secreted protein acidic and rich in cysteine (SPARC) secreted by extracellular matrix components can activate the expression of the WNK1 protein to promote the migration and invasion of lung cancer cells." (PMID 35313857, 2022). "KRT19, SPARC, SPOCK, LINC00707 (lung cancer promoting lincRNA), FOSL1 and AXL (identified as downstream targets of TS as they appeared in both signatures) were qPCR validated in both cell lines." (PMID 33024270, 2021). "Intriguingly, platelet factor 4 (PF4), an endocrine factor with overexpression correlating with decreased overall survival of patients with lung cancer, emerged as a central node connected with high confidence to SRGN, SPARC, CLU and CCL5." (PMID 31215484, 2019). "Plasma samples from lung cancer patients and healthy heavy-smokers controls were tested for levels of COL11A1 and COL10A1 (n = 57 each) and SPARC (n = 90 each)." (PMID 30227835, 2018). "In lung cancer cells and mouse tumor models, inhibiting the expression of WNK1 can reduce the expression of N-cadherin and smooth muscle actin induced by secreted protein acidic and rich in cysteine (SPARC)." (PMID 37652923, 2023). "Even if this is not surprising for many methylated genes in lung cancer, the role of SPARC in this context is novel." (PMID 32580473, 2020). "On the other hand, negative expression of SPARC in lung cancer cells indicates a poor prognosis for the overall survival of these patients." (PMID 28969021, 2017). "To demonstrate the potential clinical utility of ECM-related proteins as lung cancer circulating biomarkers, we analyzed by ELISA assay matched plasma samples from 57 patients (TU) and 57 controls (CTR) for COL11A1 and COL10A1 and from 90 patients (TU) and 90 controls (CTR) for SPARC." (PMID 30227835, 2018). "This study revealed that SPARC activated with no lysine (K) kinase 1 (WNK1) and its signaling pathways in lung cancer cells, and in a murine tumor model." (PMID 28969021, 2017). "The IGFBP2, CTGF, JAG1, and SPARC promoters are most active in the primary culture of human fibroblasts IVP-9TS, while the IGFBP2 and JAG1 promoters virtually are not active in the epithelial cells of the lung cancer Calu-1." (PMID 33804861, 2021).
neuroblastoma (32 papers, 2006 to 2024). Neuroblastoma (NB) is the most common solid, extracranial childhood tumor. "We found that when ER stress was inhibited, apoptosis was significantly reduced, which further confirms the role of ER stress in the signaling cascade associated with SPARC overexpression leading to autophagy-mediated apoptosis in neuroblastoma cells." (PMID 23123816, 2013). "Our study was also focused on understanding the specific pathways associated with SPARC overexpression that induce ER stress, which in turn elicit autophagy-mediated apoptosis in neuroblastoma." (PMID 23123816, 2013). "In the present study, we attempted to elucidate the efficacy of SPARC overexpression together with radiation therapy as an efficient way to induce apoptosis in neuroblastoma as well as investigate associated molecular mechanisms." (PMID 23123816, 2013). "In the present study, we attempted to elucidate the molecular mechanisms and signaling cascades associated with SPARC overexpression in combination with radiation therapy that eventually leads to autophagy-mediated apoptosis in neuroblastoma." (PMID 23123816, 2013). "Hence, we also investigated the involvement of autophagy as an event associated with SPARC overexpression and induction of apoptosis in neuroblastoma." (PMID 23123816, 2013). "SPARC overexpression in neuroblastoma cells inhibited neo-vascularization in vivo in a mouse dorsal air sac model." (PMID 37509139, 2023). "The effectiveness of SPARC as an anti-angiogenic factor was demonstrated in combination with radiotherapy in neuroblastoma." (PMID 34209679, 2021). "SPARC reduced radiotherapy-induced angiogenesis by down-regulating VEGF-A via miR-410 as well as tumor size in subcutaneous mouse tumor models of neuroblastoma." (PMID 34209679, 2021). "In SPARC peptide-treated neuroblastoma xenografts, a reduction of the quantity of ECs as well as normalization of blood vessel architecture were detected compared to control." (PMID 34209679, 2021). "AAV vector-mediated overexpression of DCN in neuroblastoma influenced macrophage function and led to an upregulation of Secreted Protein Acidic and Rich in Cysteine (SPARC), which plays an important role in cell growth and angiogenesis." (PMID 32674264, 2020). "Another study used the ex ovo chicken CAM to evaluate the effects of radiation combined with SPARC (secreted protein acidic and rich in cysteine) overexpression in neuroblastoma cells and describes a SPARC-induced reduction in radiation-induced angiogenesis." (PMID 31591362, 2019). "To investigate if SPARC mediated the increased deposition of lipids in neuroblastoma tumors by binding and transporting albumin loaded with FA, we characterized the interaction between the two proteins." (PMID 27776337, 2016). "In this study, we investigated the effects of stroma-derived SPARC on tumor growth using a novel in vivo stroma-rich neuroblastoma model." (PMID 27776337, 2016). "In this study, we investigated the effects of stroma-derived SPARC on tumor growth using a novel neuroblastoma model that mimics stroma-rich neuroblastoma tumors." (PMID 27776337, 2016). "Further investigations of the therapeutic potential of SPARC for children with neuroblastoma are warranted." (PMID 27776337, 2016). "We have also synthesized and tested SPARC peptides that structurally correspond to the follistatin domain of the protein and showed that they have potent anti-neuroblastoma activity." (PMID 27776337, 2016). "In neuroblastoma, SPARC is expressed in the stromal Schwannian cells and functions as a tumor suppressor." (PMID 27776337, 2016). "Taken together, these results illustrate the critical role of ER stress in regulating autophagy-mediated apoptosis in SPARC-overexpressed neuroblastoma cells and radiation treatment." (PMID 23123816, 2013).
neuroblastoma (continued). "In conclusion the results impart new insights regarding ER stress-mediated apoptosis in SPARC-overexpressed cells that should be explored further as a potential therapeutic option for neuroblastoma." (PMID 23123816, 2013). "The results of the present study demonstrate that the combination treatment of SPARC overexpression and irradiation induces apoptosis in a synergistic manner in neuroblastoma cells." (PMID 23123816, 2013). "Next, the contributory role of ER stress to induce apoptosis as a result of JNK activation by SPARC overexpression was tested using an ER stress inhibitor in pSPARC-transfected and irradiated neuroblastoma cells." (PMID 23123816, 2013). "Increased expression of LC3 was observed for SPARC-overexpressed neuroblastoma cell lines, which confirms autophagy as a part of the molecular events leading to apoptosis." (PMID 23123816, 2013). "A significant increase of these molecules in pSPARC treated cells indicated a direct involvement of autophagy in SPARC induced apoptosis in neuroblastoma." (PMID 23123816, 2013). "In this study, initially, the role of SPARC overexpression to induce apoptosis by itself and in combination with radiation was investigated in neuroblastoma cells." (PMID 23123816, 2013). "While a High SPARC level indicates poorer prognosis in some tumors, SPARC expression in neuroblastoma inhibits angiogenesis and impairs tumor growth." (PMID 22321704, 2012). "SPARC functions as a tumour suppressor in breast, neuroblastoma, pancreatic, ovarian and lung cancers." (PMID 22957090, 2012). "Recently, two antiangiogenic SPARC peptides have recently been shown to inhibit the progression of neuroblastoma tumors both in vitro and in vivo, heralding an optimistic future for SPARC as an antivascular cancer therapeutic." (PMID 22481923, 2012). "On a translational level, two antiangiogenic SPARC peptides have recently been shown to inhibit the progression of neuroblastoma tumors both in vitro and in vivo, heralding an optimistic future for SPARC as an antivascular cancer therapeutic." (PMID 22481923, 2012). "The SPARC blocks angiogenesis in vitro and in vivo in neuroblastoma and is one of the key contributors to the anti-angiogenesis activity of the Schwann cell-conditioned medium." (PMID 20087345, 2010). "Studies from our laboratory have demonstrated that Schwann cells also influence neuroblastoma tumor growth by secreting inhibitors of angiogenesis, the most potent of which is Secreted Protein Acidic and Rich in Cysteine (SPARC)." (PMID 20525313, 2010). "For example, in neuroblastoma SPARC impairs tumour growth, while in another type of brain cancer, glioblastoma, SPARC induces metastasis and invasion." (PMID 18458674, 2008). "Thus, ER stress plays a critical role in the regulation of autophagy-mediated apoptosis in SPARC-overexpressing neuroblastoma cells and radiation therapy." (PMID 38254665, 2024). "High levels of purified SPARC act as an inhibitor of both neuroblastoma growth and angiogenesis." (PMID 36430810, 2022). "SPARC is considered by some as a cancer therapeutic agent due to its ability to inhibit proliferation and enhance apoptosis in the ovary, colorectum, pancreas, neuroblastoma, and leukemia." (PMID 36430810, 2022). "However, our results are aligned with other studies suggesting that Notch inhibition increased SPARC expression in neuroblastoma, astrocytoma, and medulloblastoma." (PMID 34069142, 2021). "In neuroblastoma cells, overexpression of SPARC can inhibit endothelial cell formation and cell proliferation, including induction of programmed cell death and the inhibition of angiogenic factors expression, such as FGF VEGF, PDGF, and MMP-9 in endothelial cells." (PMID 29262657, 2017). "We found that palmitate induced significant lipotoxicity in neuroblastoma cell lines cultured in hypoxic conditions, suggesting that SPARC may promote lipotoxicity and neuroblastoma cell death by increasing the delivery of albumin-bound FA." (PMID 27776337, 2016).